ZNF217 (zinc finger protein 217)
Diseases named in the same sentence as ZNF217 in open-access papers (continued):
Sharing a sentence is not in itself a finding about the gene and the disease.
ovarian carcinoma (14 papers, 2003 to 2026). A malignant neoplasm originating from the surface ovarian epithelium. "Consistently, ZNF217 overexpression is associated with poor prognosis in both mouse models and ovarian cancer patients." (PMID 41345234, 2025). "Like in ovarian cancer cells, ZNF217 overexpression caused a significant increase in cell proliferation, migration, and invasion through matrigel in both FT237 and FT282 cells." (PMID 41345234, 2025). "For example, ZNF217 overexpression is associated with poorly differentiated tumors and the progression of ovarian cancers." (PMID 34439859, 2021). "Comparison of basal ZNF217 levels across six different ovarian cancer cell lines and two immortalized fallopian tube cell lines revealed higher ZNF217 levels in ovarian cancer cells." (PMID 41345234, 2025). "As ZNF217’s ability to bind DNA is critical for its oncogenic function, we determined the effect of overexpressing ZNF217 on the ovarian cancer cell’s transcriptome." (PMID 41345234, 2025). "Future studies focusing on ZNF217 levels in these pre-cancerous lesions will help us better understand ZNF217’s role and its clinical significance during the early stages of ovarian cancer progression." (PMID 41345234, 2025). "Publicly available gene expression datasets show that ZNF217 expression is significantly elevated in several cancers, including ovarian cancer." (PMID 41345234, 2025). "To determine how ZNF217 impacts chemoresistance, we treated control and ZNF217-overexpressing ovarian cancer cells to carboplatin, paclitaxel, and doxorubicin and measured their impact on cell viability." (PMID 41345234, 2025). "Using multiple clinically relevant in vitro and in vivo models, we show that ZNF217 drives ovarian cancer progression by impacting multiple important steps in the metastatic process." (PMID 41345234, 2025). "As ZNF217 is overexpressed in several cancers, these approaches will likely benefit patients well beyond ovarian cancer." (PMID 41345234, 2025). "Collectively, our data show that ZNF217 is a potent oncogene that can impact ovarian cancer progression and metastasis by impacting multiple steps involved in this process and can also enable the tumor cells resist chemotherapeutics." (PMID 41345234, 2025). "The ability of ovarian cancer cells to migrate and invade through matrigel were also negatively impacted by ZNF217 depletion." (PMID 41345234, 2025). "Our data also shows that ZNF217 can impact ovarian cancer progression at several different stages including the transition of early-stage tumors to aggressive metastatic disease." (PMID 41345234, 2025). "To address these limitations, we used multiple clinically relevant reagents and ovarian cancer models to comprehensively investigate how ZNF217 levels impacts the different steps in ovarian cancer metastasis and therapeutic response." (PMID 41345234, 2025). "As increased migratory and invasive potential is dependent on the acquisition of a more mesenchymal state, we determined if ZNF217 expression induces EMT in ovarian cancer cells." (PMID 41345234, 2025). "We demonstrate that Zinc Finger Protein 217 (ZNF217) is a key pro-metastatic factor in ovarian cancer cells." (PMID 41345234, 2025).
ovarian carcinoma (continued). "To ascertain potential correlation between ZNF217 and clinical outcome in ovarian cancer patients, we analyzed data from 1435 ovarian cancer patients that is publicly available through KmPlotter14,15." (PMID 41345234, 2025). "Collectively, our data demonstrates that ZNF217 overexpression impacts several critical steps involved in ovarian cancer progression and metastasis." (PMID 41345234, 2025). "For instance, overexpression of ZNF217 in ovarian cancer cells accelerates cell proliferation and significantly increases the proportion of cells in the S-phase 46." (PMID 40083704, 2025). "Next, we tested if ZNF217 depletion would sensitize ovarian cancer cells to these chemotherapeutic agents." (PMID 41345234, 2025). "Our data reveal that ZNF217’s potential to function as an oncogene and drive metastasis in ovarian cancer cells is dependent on its ability to bind DNA and transcriptionally regulate genes." (PMID 41345234, 2025). "ZNF217 depletion impairs ovarian cancer metastases and sensitizes them to extant chemotherapeutics such as carboplatin, paclitaxel, and doxorubicin." (PMID 41345234, 2025). "To determine if there is a link between ZNF217 levels and chemoresistance in ovarian cancer patients we analyzed clinical data that are publicly available through the KM-plotter database." (PMID 41345234, 2025). "The genomic locus harboring ZNF217, 20q13.2, is amplified in 31% ovarian cancer cases, 40% of which have increased ZNF217 mRNA expression." (PMID 41345234, 2025). "Another work conducted on epithelial ovarian cancer (EOC) identified a novel lncRNA OIP5 antisense RNA 1 (OIP5-AS1)/miR-137/ZNF217 regulatory circuit that accelerates ovarian cancer progression." (PMID 36551531, 2022). "In vivo, constitutive expression of ZNF217 in breast or ovarian cancer cells stimulated the growth and the rate of tumor formation." (PMID 26431164, 2015). "The prognostic value of ZNF217 protein levels in ovarian carcinoma has been found in one study (univariate analysis, p = 0.042), but not in two others." (PMID 26431164, 2015). "Thus, our data establishes ZNF217 as a potent oncogene in ovarian cancer cells that impacts multiple steps in the metastatic process and a potential therapeutic target." (PMID 41345234, 2025). "A previous study suggested that ZNF217 could potentially function as an oncogene in ovarian cancer cells." (PMID 41345234, 2025). "The resistance across a confluent OVCA420-ZNF217 monolayer was consistently lower suggesting that these cells have weaker tight junctions, which further supports ZNF217’s ability to promote ovarian cancer cell migration." (PMID 41345234, 2025). "Thus, our data establishes ZNF217 as a critical factor driving ovarian cancer progression and highlights its potential as an actionable therapeutic target to improve clinical outcome." (PMID 41345234, 2025). "Thus, by impacting several processes that are vital in the progression of primary tumor to lethal metastatic disease, ZNF217 acts as a potent oncogene in ovarian cancer cells." (PMID 41345234, 2025). "Taken together, our data suggests that ZNF217 overexpression induces largescale gene expression changes in ovarian cancer cells, which increases their proliferation, suppresses apoptosis, promotes the acquisition of a more mesenchymal state, and induces extracellular matrix reorganization." (PMID 41345234, 2025). "We demonstrate that ZNF217 functions as a potent oncogene in ovarian cancer cells." (PMID 41345234, 2025). "To ascertain if ZNF217’s role as an oncogene in ovarian cancer cells is dependent on its ability to function as a transcription factor, we tested if the ZNF217 DNA binding mutant (ZNF217-H489A) can rescue the phenotypes observed upon ZNF217 knockdown." (PMID 41345234, 2025). "Despite these compelling data, ZNF217’s precise role in ovarian cancer remains poorly understood." (PMID 41345234, 2025).
ovarian carcinoma (continued). "Interestingly, our data reveal that ZNF217 overexpression also enables ovarian cancer cells to resist extant chemotherapeutics and can thus contribute to the poor clinical outcome." (PMID 41345234, 2025). "Therefore, future studies aimed at identifying direct downstream targets of ZNF217 in ovarian cancer cells will help further understand how ZNF217’s mediates its oncogenic effects in these cells." (PMID 41345234, 2025). "Finally, we show that ZNF217 levels dictate the response of ovarian cancer cells to multiple chemotherapeutic drugs." (PMID 41345234, 2025). "Interestingly, when ZNF217 is silenced in ovarian cancer in vitro, the KRT4 gene was also significantly down-regulated." (PMID 34062972, 2021). "In addition, Sun and colleagues performed microarray analysis of gene expression in ovarian cancer with silencing of the ZNF217 gene." (PMID 27768596, 2016). "Altogether, these studies demonstrate that ZNF217 is a new oncogene that drives neoplastic progression in breast and ovarian cancers, and may act interdependently with eEF1A2." (PMID 26431164, 2015). "Finally, eEF1A2 silencing reversed resistance to apoptosis induced by ZNF217 overexpression, thus highlighting eEF1A2 as contributing towards the ZNF217-induced neoplastic properties of these precursor cells of ovarian carcinomas." (PMID 26431164, 2015). "However, it is still unknown if ZNF217 levels are elevated in early stages of ovarian cancer in patients such as in the pre-cancerous serous tubal intraepithelial carcinoma (STIC) lesions." (PMID 41345234, 2025). "Among ovarian cancer cells, OVCA420, OVCAR4, and ALST cells expressed lower ZNF217 levels compared to TYK-Nu cells." (PMID 41345234, 2025). "The same study also confirmed downregulation of PRSS8 after silencing ZNF217 expression indicating the significance of ZNF217 as a key regulator and suggesting PRSS8 as a potential biomarker in ovarian carcinomas." (PMID 23319948, 2012). "A significant increase in ovarian cancer cell’s ability to attach to ECM proteins such as fibronectin and collagen type I alpha 1 chain (COL1A1) was observed upon ZNF217 overexpression." (PMID 41345234, 2025). "To confirm that ZNF217’s effect on ovarian cancer metastasis and survival is not dependent on the strain of immunodeficient mice used, we repeated these studies using a different strain of immunodeficient mice, the NOD scid gamma (NSG) mice." (PMID 41345234, 2025). "Amplification of 20q13 may be particularly heterogeneous as AURKA, TGIF2, PTPN1 and ZNF217, and ADRM1, and other genes, have been cited as drivers of 20q13 amplification in ovarian cancer." (PMID 19419571, 2009). "Applied to six cancer types including renal, breast, pancreatic, head and neck, colorectal, and ovarian cancers, TeaCNV delineated polyclonal architectures and revealed distinct chromatin accessibility patterns driven by CNVs in key driver genes, including AKT2, ZNF217, and SOX2." (PMID 42202285, 2026).
prostate carcinoma (13 papers, 2007 to 2024). A carcinoma that arises from epithelial cells of the prostate gland. "In particular, Sehrawat and colleagues demonstrated that LSD1 gene regulation in prostate cancer is mediated by interaction with ZNF217 independently of its demethylase activity." (PMID 36414381, 2023). "For example, ZNF217 expression is predominantly increased in prostate cancer (PCa) and promotes PCa growth." (PMID 32742190, 2020). "It has been reported that miR-503 inhibits prostate cancer progression by repressing ZNF217 expression." (PMID 28602785, 2017). "Collectively, this study underscored that elevated expression of ZNF217 promotes prostate cancer growth by restraining FPN-conducted iron egress." (PMID 27768596, 2016). "Although we and other studies indicated ZNF217 expression was increased in prostate cancer (PCa), the factors mediating its misregulated expression and their oncogenic activity remain largely unexplored." (PMID 27768596, 2016). "In other cancer types, both mRNA and protein levels for ZNF217 have been shown to correlate with patient outcomes, including breast, ovarian, colon and prostate cancer types [recently showed by 29, and reviewed by 30, 31]." (PMID 27363029, 2016). "Furthermore, while this manuscript was under review, another study was published demonstrating that the GATA3-driven expression of miR-503 represses ZNF217 in prostate cancer." (PMID 27539783, 2016). "In addition, miR‐503 accompany with GATA3, targets ZNF217 and suppresses prostate cancer." (PMID 38173189, 2024). "Zinc finger protein 217 (ZNF217) was proven as miR-503 target, it is demonstrated that GATA3/miR-503 axis suppressed the progression of prostate cancer by inhibiting ZNF217 expression." (PMID 33762949, 2021). "Intriguingly, this demethylase-independent effect was explained in part by activation of a lethal prostate cancer gene network, in collaboration with LSD1’s binding protein, ZNF217." (PMID 31805626, 2019). "MiR-203 also inhibits prostatic cancer metastatic potential by suppressing RAP1A (ras-related protein 1A) expression and suppresses ZNF217 (zinc finger protein 217) oncogenic activity in colorectal cancer." (PMID 31073374, 2019). "In prostate cancer miR-203 exists in a double negative feedback loop with the EMT transcription factor SNAI2, along with ZNF217 and miR-203 was previously shown to differentiate EAC from BE and decreased expression associated with poorer EAC patient outcome." (PMID 27363029, 2016).
colorectal cancer (11 papers, 2011 to 2026). A primary or metastatic malignant neoplasm that affects the colon or rectum. "ZNF217 is a transcription factor associated with poor prognosis in various carcinomas, especially increased metastatic potential in colorectal cancer." (PMID 27974047, 2016). "miR-203 targeted ZNF217 mRNA for silencing and was associated with decreased cell migration and invasion in colorectal cancer cells." (PMID 26431164, 2015). "ZNF217 mutations were significantly associated with early-stage colorectal cancer." (PMID 36439454, 2022). "Finally, ZNF217 is overexpressed in colorectal carcinoma tissues and is associated with tumor malignant clinicopathological features, which may promote colorectal carcinoma progression by inducing cell migration and invasion." (PMID 34712617, 2021). "ZNF217 protein levels were associated with aggressive clinical markers (p < 0.05 and p < 0.05) and shorter OS (univariate analysis, p = 0.028) in colorectal cancer and with shorter RFS (univariate analysis, p = 0.0016) and OS (univariate analysis, p = 0.019) in gastric carcinoma." (PMID 26431164, 2015). "Further observations revealed that ZNF217 mRNA and protein were overexpressed in primary prostate carcinoma versus normal prostate tissue (p < 0.05 and 14 out of 23 analyzed cases, respectively) and in colorectal carcinoma tissues associated with poor clinicopathological features (p < 0.05)." (PMID 26431164, 2015). "Further possible events that favoured transformation are the gain of the oncogenes GNAS (a PDAC driver gene), LINC00659 (an oncogene in colorectal cancer), and ZNF217 (an oncogene in many solid tumours, including PDAC)." (PMID 36289850, 2022). "Recently, it was found that ZNF217 is overexpressed and enhances cell migration and invasion in colorectal carcinoma." (PMID 31756991, 2019). "Conversely, ZNF217 extinction allowed reversion of these phenotypes in breast, ovarian and colorectal cancer cells." (PMID 26431164, 2015). "In our case-series, 38% of tumors showed a gain at 20q chromosome arm, where multiple candidate oncogenes associated with increased proliferative activity, reduced survival and progression of colorectal cancer (e.g. ZNF217, CYP24 and AURKA), are mapped." (PMID 22099067, 2011). "However, the role of ZNF217 in colorectal cancer metastasis is still unknown." (PMID 36439454, 2022). "Increased expression of the ZNF217 gene in the beef tallow dietary group may be one of the mechanisms explaining the high correlation between red meat consumption and increased occurrences of colorectal cancer since red meat contains substantial amounts of palmitic acid." (PMID 31756991, 2019).
cervical cancer (6 papers, 2020 to 2023). A primary or metastatic malignant neoplasm involving the cervix. "According to studies, CTBP1-DT targets miR-3163 to increase ZNF217 expression, which in turn accelerates the progression of cervical cancer." (PMID 37124619, 2023). "LncRNA CTBP1-DT has been shown to elevate ZNF217 expression in cervical cancer and regulate phosphatase and tensin homologue to suppress OC cell proliferation." (PMID 34887384, 2021). "LncRNA CTBP1-DT, a newly identified lncRNA, regulates cervical cancer progression by sponging miR-3163 to upregulate ZNF217, which could promote cell proliferation in hepatocellular carcinoma by regulating the miR-623/cyclin D1 axis." (PMID 34887384, 2021). "In cervical cancer, CTBP1-AS2 facilitates cervical cancer progression by sponging miR-3163 to upregulate ZNF217 expression." (PMID 35039872, 2022). "In cervical cancer, Yang and colleagues discovered that ZNF217 is targeted by miR-3163 and that the lncRNA CTBP1 antisense RNA 2 (CTBP1-AS2) regulates cancer progression after miR-3163 sponging to upregulate ZNF217." (PMID 36551531, 2022).